PTTG1 (PTTG1 regulator of sister chromatid separation, securin)
Diseases named in the same sentence as PTTG1 in open-access papers (continued):
Sharing a sentence is not in itself a finding about the gene and the disease.
lung adenocarcinoma (10 papers, 2021 to 2025). A carcinoma that arises from the lung and is characterized by the presence of malignant glandular epithelial cells. "As a hub gene associated with tryptophan metabolism, PTTG1 plays a promotive role in lung adenocarcinoma progression and is a potential predictive biomarker for clinical outcomes and immunotherapy response in lung adenocarcinoma, which requires further prospective studies and larger populations." (PMID 39144144, 2024). "For example, the blockade of PTTG1 enhances radiation-induced antitumor immunity in lung adenocarcinoma." (PMID 37243239, 2023). "Moreover, the study on lung adenocarcinoma cells revealed that PTTG1 protein expression is highly upregulated in lung adenocarcinoma tissues, which is positively correlated with lymphatic invasion of the tumor." (PMID 40072059, 2025). "The findings suggest that PTTG1 could be a potential target for developing immunotherapeutic strategies for lung adenocarcinoma." (PMID 40072059, 2025). "PTTG1 is one of the key genes, and knockdown of PTTG1 in vitro decreases lung adenocarcinoma cell proliferation and migration and promotes apoptosis and down-regulation of tryptophan metabolism regulators in lung adenocarcinoma cells." (PMID 39144144, 2024). "The role of PTTG1 in lung adenocarcinoma is unknown, which prompted us to explore the role of PTTG1 as a potential prognostic biomarker for lung adenocarcinoma." (PMID 39144144, 2024). "We also observed a down-regulation of the transcriptional level of TDO2 in A549 cells, suggesting that PTTG1 may affect the level of tryptophan metabolism in lung adenocarcinoma cells." (PMID 39144144, 2024). "Previously, the oncogenic roles of PTTG1 were also reported in lung adenocarcinoma (LUAD)." (PMID 35251171, 2022). "Our previous study indicated that PTTG1 could promote the occurrence of EMT through the PI3K/Akt/Snail signaling pathway in lung adenocarcinoma." (PMID 36059662, 2022). "In this comprehensive study, we explored the roles of the pituitary tumor-transforming gene (PTTG) family, including PTTG1, PTTG2, and the pseudogene PTTG3P in lung adenocarcinoma (LUAD)." (PMID 40877987, 2025). "In follow-up experiments, we found that PTTG1 promoted the proliferation, migration, and EMT of lung adenocarcinoma cells, as well as inhibited apoptosis of lung adenocarcinoma cells." (PMID 39144144, 2024). "PTTG1 expression at the protein level was higher in various tumors, including BRCA, COAD, and lung adenocarcinoma (LUAD)." (PMID 35281830, 2022).
non-small cell lung carcinoma (10 papers, 2006 to 2025). A group of at least three distinct histological types of lung cancer, including non-small cell squamous cell carcinoma, adenocarcinoma, and large cell carcinoma. "For instance, Li and colleagues have reported that PTTG1 promotes cell proliferation, migration, and invasion in the non-small cell lung cancer cells." (PMID 32272902, 2020). "Patients with non-small cell lung cancer with higher expression levels of the PTTG1 gene exhibited shorter OS times." (PMID 32824814, 2020). "High NCAPG2 expression is associated with advanced clinical tumor stage and reduced survival time in patients with lung adenocarcinoma, and PTTG1 has been correlated with non-small cell lung cancer progression and is an independent poor prognostic factor in patients with non-small cell lung cancer." (PMID 40559622, 2025). "Intriguingly, it has been shown that SP17/AKAP4/PTTG1 could induce an immunogenic response in non-small cell lung cancer patients." (PMID 35768832, 2022). "Similarly, the second member, PTTG1, has been reported to promote migration and invasion in non-small cell lung cancer." (PMID 32824814, 2020). "It has been suggested that miR-186 could inhibit the cell proliferation, migration and invasion of non-small cell lung cancer by modulating pituitary tumor-transforming gene-1 (PTTG1)." (PMID 27966444, 2016). "Expression of PTTG-1 was examined immunohistochemically on formalin-fixed, paraffin-embedded tissue sections of 136 patients with small cell lung cancer (SCLC) and 91 patients with non-small cell lung cancer (NSCLC), retrospectively." (PMID 16426442, 2006).
esophageal squamous cell carcinoma (9 papers, 2015 to 2025). Esophageal squamous cell carcinoma (ESCC) is a type of esophageal carcinoma (EC) that can affect any part of the esophagus, but is usually located in the upper or middle third. "Comprehensive analysis of PTTG1 expression in esophageal squamous cell carcinoma (ESCC) based on gene microarrays, in-house immunohistochemistry (IHC), public RNA-seq, and in-house RNA-seq." (PMID 33552118, 2020). "MiR-655-3p expression is reduced in several cancers and overexpression of miR-655 act as a tumor suppressor by targeting pituitary tumor-transforming gene-1(PTTG1) in esophageal squamous cell carcinoma metastasis." (PMID 27259866, 2016). "Moreover, PTTG1 promotes the invasion of esophageal squamous cell cancer cells by inducing epithelial–mesenchymal transformation, and PTTG1 is involved in inducing epithelial–mesenchymal transformation by activating the expression of GLI1 in esophageal squamous cell carcinoma." (PMID 33123466, 2020). "High expression levels of PTTG3P, PTTG1, and PTTG2 have been observed in esophageal squamous cell carcinoma (ESCC) patients and cell lines." (PMID 36770654, 2023). "In vitro studies have confirmed that exogenously the overexpression of PTTG3P promotes the transcription of its parental genes PTTG1 and PTTG2 in esophageal squamous cell carcinoma cells." (PMID 32824814, 2020).
leukemia (9 papers, 2006 to 2025). A malignant (clonal) hematologic disorder, involving hematopoietic stem cells and characterized by the presence of primitive or atypical myeloid or lymphoid cells in the bone marrow and the blood. "In many types of cancer cells including leukemia, pituitary tumor‐transforming gene 1 (PTTG1) is highly expressed and regulate cell proliferation." (PMID 39830909, 2025). "Pituitary tumor-transforming gene 1 (PTTG1), an oncoprotein that regulates cell proliferation, is highly expressed in several types of cancer cells including leukemia." (PMID 29649138, 2018). "Our findings indicated that the PTTG1 protein plays a critical role in the different responses to luteolin treatment in undifferentiated and differentiated leukemia cells." (PMID 29649138, 2018). "In this study, microarray analysis was carried to elucidate the molecules involved in the PTTG1-potentiated anti-cancer effect of luteolin on leukemia cells." (PMID 29649138, 2018). "To clarify the role of PTTG1 in the anti-leukemic effects of luteolin, we further generated PTTG1-knockdown leukemia cells in this experiment." (PMID 29649138, 2018). "Our findings revealed that high levels of PTTG1 protein expression in leukemia will promote cell-cycle progression." (PMID 29649138, 2018). "In this study, we clearly demonstrated that PTTG1 gene expression is significantly down-regulated through the inhibition of PTTG1 promoter activity in PMA-primed THP1 or HL-60 leukemia cells." (PMID 23977008, 2013). "In this study, we showed that PTTG1 is abundantly expressed in several leukemia cell lines; in contrast, its expression in normal PBMCs and well-differentiated macrophages is undetectable." (PMID 23977008, 2013). "Abundant levels of the PTTG1 protein were detected in leukemia cell lines, including HL-60, K-562, HEL, U937 and THP1 cells." (PMID 23977008, 2013). "In this study, we demonstrated that the oncogene PTTG1, which is overexpressed in leukemia cells, is transcriptionally repressed by the tumor suppressor KLF6 in response to PMA-induced myeloid differentiation." (PMID 23977008, 2013). "Additional studies will help validate the role of PTTG1 in leukemia differentiation and its effects on tumorigenesis." (PMID 23977008, 2013). "We then investigated the effect of PMA-induced myeloid cell differentiation on PTTG1 expression in these leukemia cell lines." (PMID 23977008, 2013). "The overexpression of PTTG1 has been found in several poorly differentiated leukemia cell lines (i.e., HL-60, K-562, MOLT-4 and Raji) and lymphoid neoplasias." (PMID 23977008, 2013). "It triggers leukemia cells apoptosis through modulating the differential expression of PTTG1." (PMID 36422285, 2022). "Furthermore, PTTG1 knockdown by shRNA in leukemia cells suppressed cell proliferation, arrested cell-cycle progression and impaired the effectiveness of luteolin on cell-cycle regulation." (PMID 29649138, 2018). "The detailed molecular mechanism involved in PTTG1 overexpression in these leukemia cells remains unclear." (PMID 23977008, 2013). "Because PTTG1 overexpression promotes tumorigenesis and metastasis and may maintain the precursor stages of leukemia cells, PTTG1 knockdown could be a potential option for cancer therapy." (PMID 23977008, 2013). "Thus, it appears that PTTG1 suppression in PMA-primed leukemia cells goes through the activation of the PKC/ERK/KLF6 pathway." (PMID 23977008, 2013). "To elucidate this hypothesis, we generated PTTG1-knockdown cells by shRNA in leukemia cell lines." (PMID 29649138, 2018). "Various researchers have found an abnormally high expression of PTTG1 in a wide range of human primary tumors such as those found in the ovary, testis, kidney, colon, thyroid, pituitary, liver, adrenal, and breast as well as in a range of tumor cell lines such as melanoma, leukemia, and lymphoma." (PMID 19014669, 2008).
leukemia (continued). "PTTG-1 is physiologically expressed in normal tissues of different organs such as testis, colon and lung while an overexpression was observed in several malignant tumors and cancer cell lines, including carcinomas of the gastrointestinal tract, breast, lung, as well as in leukemia and lymphoma." (PMID 16426442, 2006). "The PTTG1 mRNA and protein levels in PMA-primed leukemia cells were increased when BIM and U0126 were used." (PMID 23977008, 2013). "However, the PTTG1 protein is dramatically down-regulated in normal PBMCs and PMA-differentiated leukemia cells." (PMID 29649138, 2018). "In leukemia cells with down-regulated PTTG1 expression, the cells did not pass the G1/S checkpoint, and the cell cycle was arrested in the G1 phase." (PMID 29649138, 2018). "Early studies demonstrated that PTTG1 was highly expressed in approximately 70 % of patients with leukaemia, lymphoma or other myelodysplastic diseases but not in healthy donors." (PMID 26445238, 2015). "Consequently, we investigated whether PTTG1 down-regulation was dependent on the PKC and MAPK/ERK pathways in PMA-primed leukemia cells." (PMID 23977008, 2013).
seminoma (9 papers, 2016 to 2023). A radiosensitive malignant germ cell tumor found in the testis (especially undescended), and extragonadal sites (anterior mediastinum and pineal gland). "We previously reported that PTTG1’s oncogenic properties, specifically in seminoma, were strictly associated with its nuclear distribution." (PMID 38069214, 2023). "We previously demonstrated its contribution in seminoma tumors, showing that PTTG1’s oncogenic activity was associated with its nuclear localization." (PMID 38069214, 2023). "This prompted us to deepen our understanding of the molecular mechanism underlying the role of PTTG1 in seminoma tumor progression, with a special focus on EMT process." (PMID 36230799, 2022). "All together, these data support the pivotal role of nuclear PTTG1 in driving the invasion-prone cell population of human seminoma, and shed a light on the underlying mechanism in which the interplay with ZEB1 is crucial." (PMID 36230799, 2022). "In seminoma, PTTG1 oncogenic properties were strictly linked with its nuclear localization." (PMID 36230799, 2022). "This prompted us to investigate the functional interplay between SPTBN1 and PTTG1 in seminoma tumors." (PMID 38069214, 2023). "First, we showed that the invasive behavior of seminoma cells depends on the PTTG1-mediated transcriptional activation of the MMP-2 gene." (PMID 38069214, 2023). "In human seminoma specimens, we found a strong PTTG1/SPTBN1 colocalization that decreases in areas with nuclear PTTG1 distribution." (PMID 38069214, 2023). "In fact, we formerly reported that TCAM2 retains the lowest nuclear localization of PTTG1 when compared to the other two seminoma cellular models." (PMID 38069214, 2023). "To this aim, we made use of a proteomic approach using PTTG1 immunoprecipitation in seminoma cell lines." (PMID 38069214, 2023). "To validate the interaction between PTTG1 and spectrins and their differential reciprocal binding in JKT-1, SEM-1, and TCAM2 seminoma cells, we performed PTTG1 immunoprecipitation and immunofluorescence analysis." (PMID 38069214, 2023). "In particular, we firstly reported that PTTG1’s nuclear localization was more pronounced in the seminoma periphery, which is a more invasion-prone area." (PMID 38069214, 2023). "Further studies in human seminoma tissues are needed to correlate the interplay of PTTG1/SPTBN1 with tumor staging in order to provide a translational impact for our data." (PMID 38069214, 2023). "Regardless, the significance of our research lies in the identification of SPTBN1 as a factor that is able to impair the nuclear oncogenic activity of PTTG1 in seminoma." (PMID 38069214, 2023). "To this aim, we investigated the PTTG1 interactome in seminoma cell lines showing different PTTG1 nuclear levels correlated with invasive properties." (PMID 38069214, 2023). "Thereafter, we made use of in vitro cellular model of seminoma to demonstrate the correlation between nuclear PTTG1 and a more aggressive phenotype in the JKT-1, SEM-1, and TCAM2 cell lines." (PMID 38069214, 2023). "Overall, these results suggest that SPTBN1, along with PTTG1, is a potential prognostic factor useful in the clinical management of seminoma." (PMID 38069214, 2023). "The Atlas database revealed that seminomas that contained higher nuclear PTTG1 levels showed significantly lower SPTBN1 levels in comparison to non-seminomas." (PMID 38069214, 2023). "We previously demonstrated that nuclear PTTG1 promotes seminoma tumor invasion through its transcriptional activity on matrix metalloproteinase 2 (MMP-2) and E-cadherin (CDH1)." (PMID 38069214, 2023). "We previously highlighted the eligibility of the pituitary tumor-transforming gene 1 (PTTG1) as a promising new prognostic factor for seminoma cancer progression." (PMID 38069214, 2023). "The aim of the present work was to investigate the role of PTTG1 in seminoma cancer progression, and particularly its role in the regulation of the EMT process." (PMID 36230799, 2022).
seminoma (continued). "The Atlas database interrogation revealed that in seminomas, there was an increased nuclear PTTG1 localization along with higher levels of MMP-2 compared to nonseminoma tumors." (PMID 36230799, 2022). "The present study is an extension of our previous research which showed higher PTTG1 nuclear localization in the invasion-prone cell population at the periphery of human seminoma." (PMID 36230799, 2022). "Our data enrich the molecular characterization of seminoma, suggesting that PTTG1 is a prognostic factor in seminoma clinical management." (PMID 36230799, 2022). "Lastly, we have recently demonstrated the role of PTTG1 nuclear localization in promoting invasiveness and metastatic process in different seminoma cell lines via the increase of MMP2 levels." (PMID 36230799, 2022). "We previously reported that PTTG1 expression, specifically its nuclear localization in seminoma cell lines is responsible for a more aggressive phenotype via its migratory properties, Matrigel invasion capability and MMP-2 proteolytic activity." (PMID 36230799, 2022). "We previously demonstrated the involvement of PTTG1 in the migration/invasion properties of seminoma cell lines." (PMID 36230799, 2022). "It is of note that analysis of the Atlas database of testicular tumors supported the in vivo role of the PTTG1/ZEB1/E-CAD axis in human seminoma." (PMID 36230799, 2022). "Analysis of the Atlas database of testicular tumors showed significantly lower E-Cadherin levels in seminoma, where PTTG1 showed nuclear staining." (PMID 36230799, 2022). "The Atlas database analysis confirmed the prevalent nuclear localization of PTTG1 in seminoma tumors, and the strong correlation between its nuclear localization and the increased expression of MMP2 versus nonseminoma tumors." (PMID 36230799, 2022). "Taken together, these data indicate that PTTG1 is able to transcriptionally repress E-CAD in seminoma cell lines." (PMID 36230799, 2022). "In functional assays, we further demonstrated that PTTG1/ZEB1 interaction mediates the securin oncogenic properties in seminoma cell lines." (PMID 36230799, 2022). "A previous study reported that PTTG1, an overexpressed gene in seminoma tumor, promoted the migration and invasion of tumor cells via activation of MMP-2." (PMID 35251171, 2022). "Matrigel invasion and spheroid formation assays were applied to functionally investigate PTTG1 involvement in the EMT of seminoma cell lines." (PMID 36230799, 2022). "Overall, the results of this research represent a further step in understanding the partners and interactions of PTTG1 that contribute to its oncogenic activity and represent potential prognostic factors in human seminomas." (PMID 36230799, 2022). "The findings of this paper detail the molecular pathways involved in PTTG1-mediated tumor progression in human seminoma, strengthening understanding of its role in the EMT process." (PMID 36230799, 2022). "We evaluated the ability of PTTG1 to transcriptionally suppress the E-CAD protein in seminoma cell lines." (PMID 36230799, 2022). "Overall, these data support and detail the pivotal role of PTTG1 nuclear localization as a marker of its detrimental activity in seminoma cells." (PMID 36230799, 2022). "Taken together, these results strengthen the role of PTTG1 in the EMT process in human seminomas, focusing its function on the cooperation with the transcriptional repressor activity of ZEB1, specifically on the E-CAD gene." (PMID 36230799, 2022). "Meanwhile, PTTG1 overexpression makes seminoma stem cells more invasive and aggravates neoplastic angiogenesis." (PMID 33777092, 2021). "The identification of factors responsible for progressive PTTG1 nuclear translocation will help to elucidate seminoma cancer biology and to uncover new players useful in seminoma behavior and prognosis." (PMID 33430117, 2021).